TLR8 (toll like receptor 8)
Diseases named in the same sentence as TLR8 in open-access papers (continued):
Sharing a sentence is not in itself a finding about the gene and the disease.
tumor (continued). "A subsequent activation of TLR7 and TLR8 was seen when tumor-derived exosomes (miR-21 and miR-29a) were transferred to immune cells that resulted in activation of a pro-metastatic inflammatory response leading to tumor growth and metastasis." (PMID 30574163, 2018). "The production of these mediators, together with increased antigen processing and presentation by TLR8-activated accessory cells, set the stage for a seamless transition from NK cell-mediated tumor killing to the development of a tumor antigen-specific cellular immune response." (PMID 26928328, 2016). "Comparison of the cellular co-localization of TLR7 or TLR8 with CD34 analyzed by immunofluorescence double staining revealed increased coexpression of TLR7 or TLR8 with CD34 in tumor cells, indicating that those cells were indeed cancer cells expressing the angiogenic surface molecule." (PMID 26134824, 2015). "More importantly, TLR7/TLR8 expression increased tumor growth in vivo." (PMID 26134824, 2015). "We then determined whether blockage of TLR8 signaling, responsible for the reversal of tumor-induced T-cell senescence, can also affect endogenous cAMP production in tumor cells after treatment with Poly-G3." (PMID 25231413, 2014). "Importantly, we discovered that TLR8 signaling in tumor cells can block the induction of senescence in naïve and tumor-specific effector T cells and reverse their suppressive effects in vitro and in vivo, resulting in enhanced anti-tumor immunity." (PMID 25231413, 2014). "To resolve whether the IMQ-induced aerobic glycolysis was mediated by TLR7/8, we examined TLR7 and TLR8 expression in the tumor cell lines and primary human keratinocytes." (PMID 24658058, 2014). "We further explored whether TLR8 signaling can prevent the induction of senescence and development of suppressive function in tumor-specific CD8+ TIL586 cells in this 586mel-bearing NSG mouse model." (PMID 25231413, 2014). "In addition, these studies identify a novel strategy for tumor immunotherapy through activation of TLR8 signaling in tumor cells, resulting in enhanced anti-tumor immunity." (PMID 25231413, 2014). "Furthermore, the TLR8-mediated reversal of Treg suppression can significantly induce enhanced anti-tumor immune responses mediated by tumor-specific CD8+ T cells in adoptive transfer tumor models." (PMID 25231413, 2014). "Importantly, activation of TLR8 signaling in tumor cells can block the induction and reverse the suppression of senescent naïve and tumor-specific T cells in vitro and in vivo, resulting in enhanced anti-tumor immunity." (PMID 25231413, 2014). "This study expands on previous research to further explore the role of metabolic regulation mechanism in the immunosuppressive microenvironment of OC cells and to try to investigate whether TLR8/mTOR signal may be a potential target for tumor immunotherapy in the future." (PMID 37317670, 2023). "However, the exact mechanism by which TLR8 reverses the immunosuppressive function of Tregs in the tumor microenvironment of OC remains unclear." (PMID 37317670, 2023). "The modulation of TLR7 and TLR8 responses is independent of CpG motifs or the nature of the oligodeoxynucleotides (ODNs) backbone structure, and the crosstalk between ODNs, IRMs, and TLR7 and TLR8 may be used for different clinical implications, including tumor therapy." (PMID 36476317, 2022). "Therefore, TLR8 agonists possess the potential to turn immune unresponsive “cold” tumors to immune responsive “hot” tumors, thereby addressing the urgent unmet medical need in tumor immunotherapy." (PMID 35006413, 2020). "In addition to the anti-angiogenesis induced by chelation of Cu2+, these smart nanoparticles caused further anti-tumor effects via tumor vessel obstruction (e.g., aggregation of nanochelators) and TLR-mediated immune cells stimulation (with TLR7 and TLR8 agonist), respectively." (PMID 32328480, 2020). "An alternate strategy could be to activate TLR8 signaling in tumor cells and Tregs." (PMID 32570952, 2020).
tumor (continued). "Thus, we investigated whether we can prevent the induction of T-cell senescence mediated by tumor cells in vivo by activation of TLR8 signaling in the adoptive transfer model." (PMID 25231413, 2014). "Extracellular miRNAs (e.g., miR-21/miR-29a in tumor exosomes); RNA–LL37 complexes activating TLR8 in neutrophils." (PMID 41303627, 2025). "Toll-like receptors (TLRs), including TLR2, TLR4, TLR7, TLR8, and TLR9, are critical pattern recognition receptors on TAMs, with diverse ligands such as tumor proteins, acute-phase proteins, drugs, and bacterial metabolites." (PMID 40948759, 2025). "In contrast, other loci, including RNGTT, the TLR7 and TLR8 loci, and CDH4, are constitutively or inducibly expressed also in healthy tissue and their expression in tumours is downregulated by the independent transcriptional activation of nearby RTEs." (PMID 40336011, 2025). "Tumor-T cell contact can activate cAMP pathways to trigger CD4+ T cell senescence, a process reversed by tumor cell TLR8 activation." (PMID 40860134, 2025). "Conversely, introduction an antisense targeting 5′‐half‐GlyGCC to tumour Te‐EVs abrogated p65 phosphorylation and reduced TNF‐α and IL‐6 secretion in dTHP‐1 cells via TLR8." (PMID 40326665, 2025). "In terms of modulating Treg cells for tumor immunotherapy via the TIR domain, TLR8 has been shown to reverse the immunosuppressive function of Tregs and enhance their anti-tumor activity by inhibiting glycolysis and glucose uptake." (PMID 41488647, 2025). "A pro-tumour effect of tumour cell-intrinsic TLR7 and TLR8 expression would predict that their downregulation by HERVH Xp22.2-AS transcriptional activation has an anti-tumour effect." (PMID 40336011, 2025). "explored the landscape of TLR expression in the tumor microenvironment of triple-negative breast cancer (TNBC), identifying distinct roles of TLR4 and TLR8 in the maintenance of the tumor-immune microenvironment." (PMID 38903515, 2024). "Studies have shown the potential of combining soluble Flt3L with TLR8 agonists or αCTLA-4 to improve CD8+ T-cell responses in in vitro studies and mouse tumor models." (PMID 38829139, 2024). "Tumor cells can induce TLR-mediated NF-κB activation and protumoral inflammatory process by secreting a large number of EXOs containing miRNA-21 and miRNA-29a and binding to TLR8 and TLR7 in immune cells, leading to tumor growth and metastasis." (PMID 37680720, 2023). "TLR9 activation is similar to TLR3/ TLR7/TLR8 activation and results in increased expression levels of costimulatory molecules such as TRAIL, which can induce tumor cell death, and CCR7, which promotes trafficking of APCs to lymph nodes." (PMID 37112730, 2023). "Another pre-clinical study shows an anti-tumor effect after treatment of mice with lung cancer or fibrosarcoma with the combination of a TLR3 agonist poly(I:C) and TLR8 agonists, R837 or R848." (PMID 37143666, 2023). "It is worth noting that activating TLR8 signal in tumor cells can prevent tumor cells from producing CAMP, reverse the transformation of tumor‐induced initial type, and tumor‐specific T cells into senescent cells, and thus enhance antitumor immunity in vivo." (PMID 38063246, 2023). "Tumor‐secreted microRNAs bind to murine TLR7 and human TLR8 in immune cells to trigger tumor metastasis." (PMID 37254712, 2023). "Many clinical trials attempt to enhance the anti-tumor effect by using agonists to cover both TLR7 and TLR8 targets." (PMID 36476317, 2022). "Both IMQ and RSQ can promote tumor regression through the activation of immune responses by acting as agonists for TLR-7 and TLR-7/TLR-8, respectively." (PMID 36297510, 2022). "Previous studies have shown that multiple PRRs (TLR2, TLR3, TLR4, TLR7, TLR8 and RIG‐1) in stromal cells recognise tumour cell‐derived EVs and participate in tumour metastasis." (PMID 36068649, 2022).
tumor (continued). "Studies have shown that TLRs located in cells (TLR3, TLR7, TLR8, or TLR9) are more effective in triggering anti-tumor immune responses than extracellular TLRs (TLR1, TLR2, TLR4, or TLR6)." (PMID 35965509, 2022). "The expression of TLR1, TLR3, TLR5, TLR6, TLR7, TLR8, and TLR10 show significantly decreasing trends from normal tissues to surrounding tumor tissues and to tumor tissues." (PMID 34141706, 2021). "This hypothesis was corroborated by data suggesting that tumor cells could transfer cyclic adenosine monophosphate (cAMP) to T cells via gap junctions, resulting in T-cell senescence and immunosuppression, which could be reverted by cAMP lowering via TLR8 signaling in tumor cells." (PMID 34239877, 2021). "As for the TLR8 expression in KIRC, results of gene expression analysis found an FC of 13.245 of TLR8 in tumour tissues (p=1.43E − 7)." (PMID 34531911, 2021). "Perhaps the increased TLR8 expression/activity in females results in a greater ability for VTX to increase DC activity, enhance CTX-induced NK activity and trigger robust anti-tumor immune responses." (PMID 33452311, 2021). "Altogether, these results indicate that the activation of TLR7, TLR8, and TLR9 of TAMs can change macrophages from a tumor-promoting effect to an anti-tumor effect." (PMID 33224886, 2020). "TLR8 is the only TLR that has been shown to be necessary and sufficient to reverse the suppressive function of Treg cells, resulting in strong tumor-suppressive effects." (PMID 32963529, 2020). "In another study, NFκB in macrophages was activated through binding of miR-21 and miR-29a, secreted by tumor-derived exosomes, to murine TLR7 and human TLR8, to trigger a TLR-mediated pro-metastatic inflammatory response to promote tumor growth and metastasis." (PMID 31555295, 2019). "It was represented that tumor-released miRNAs act as a ligand for TLR family, human TLR8, and murine TLR7 in immune cells that promote pro-metastatic inflammatory factors and eventually results in tumor cell movement and aggressiveness." (PMID 31291956, 2019). "It was reported that miR-21 induces inflammatory responses in macrophages by binding to murine TLR7 and human TLR8, and then triggers a TLR-mediated prometastatic inflammatory response, likely leading to tumor growth and metastasis." (PMID 29892301, 2018). "Tumor-secreted miR-21 and miR-29 act as paracrine agonist of TLRs to bind TLR7 in mouse or TLR8 in human immune cells, and ultimately lead to TLR-mediated tumor metastasis and growth." (PMID 27336891, 2016). "Tumor growth in vivo was found to be enhanced when compared to controls with empty vector PANC1 cells (TLR7+ and TLR8+, each n=5 vs. empty vector, n=4)." (PMID 26134824, 2015). "Untreated TLR7+ and TLR8+ PANC1 cells showed significantly increased tumor cell proliferation when compared to controls at 72 h after seeding (TLR7, 181% and TLR8, 182% vs. empty vector, 153%; P<0.002 and P<0.005)." (PMID 26134824, 2015). "To determine the functional role of TLR7 and TLR8 we generated TLR7 and TLR8 expressing human PANC1 cancer cells and analyzed the effects of TLR7/8 agonists (R848, resiquimod) in the inflammatory process on tumor cell proliferation and chemoresistance." (PMID 26134824, 2015). "Tumor xenograft growth of TLR7 and TLR8 transduced human PANC1 cancer cells in Balb/c nude mice was examined." (PMID 26134824, 2015). "For in vitro/in vivo studies TLR7/TLR8 overexpressing PANC1 cell lines were generated and analyzed for effects of (un-)stimulated TLR expression on tumor cell proliferation and chemoresistance." (PMID 26134824, 2015). "First, we recently demonstrated that human TLR8 signaling completely reversed the suppressive functions of naturally occurring CD4+CD25+ Treg cells and tumor-derived CD4+, CD8+, and γδ Treg cells." (PMID 25231413, 2014). "Knockdown of TLR8, MyD88, and IRAK4 in tumor cells significantly blocked the Poly-G3-mediated reversal of tumor-induced CD4+ T-cell senescence." (PMID 25231413, 2014).
tumor (continued). "It has been proposed that the anti-viral and anti-tumor effects of imiquimod in the skin are mediated by activation of TLR7 and/or TLR8 expressed by monocytes, macrophages, and plasmacytoid dendritic cells (pDCs)." (PMID 24146965, 2013). "As an agonist of TLR7 and TLR8, resiquimod (R848)-loaded β-cyclodextrin nanoparticles (CDNP-R848) induced a repolarization of M2-like TAMs shifted toward a M1-like TAM phenotype, leading to the reduction of tumor growth in multiple murine tumor models." (PMID 40050933, 2025). "TLR4 signaling promotes tumor growth, while TLR7, TLR8, and TLR9 signaling may exert anti-tumor effects." (PMID 40948759, 2025). "TLR8 agonists reduce cAMP production in tumor cells and inhibit glycolysis of tumor-derived Tregs without interfering with effector T cell metabolism, thereby preventing T cell senescence." (PMID 38415245, 2024). "The TLR8 agonist VTX-2337 (motolimod) can effectively activate TLR8, enhance NK cell function by indirectly activating NK cells through the stimulation of monocytes or myeloid DCs (mDCs), and increase tumor-directed ADCC in conjunction with cetuximab." (PMID 39234249, 2024). "Tumour‐secreted miR‐21 and miR‐29 also act as paracrine agonists of TLRs, which through interacting with either murine TLR7 or human TLR8 on immune cells transmit signals between tumour cells and the microenvironment, leading to regulation of tumour metastasis." (PMID 33336901, 2021). "Accumulating evidence indicated that activation of TLR8 could reverse Treg and MDSC mediated immune suppression resulting in strong tumor inhibition." (PMID 35006413, 2020). "TLR8 agonists decrease production of cAMP in tumor cells and inhibit glycolysis in tumor-derived Tregs, but do not interfere with effector T cell metabolism, thus preventing senescence of tumor-killing TILs without limiting their function." (PMID 32570952, 2020). "We did not evaluate TLR8 expression in our tumour cells, but we found the usual but unexplained male preponderance in EBV- and HPV-positive patients (74 and 76% were males, respectively)." (PMID 31238894, 2019). "However, our data revealed suppression of TLR5, TLR7, TLR8 and TLR10 in PBMCs from CRC patients, suggesting a possible flip in the expression of those receptors between the tumor and periphery which warrants further investigation." (PMID 31835892, 2019). "In particular, we demonstrate that the suppressive function of human naturally occurring CD4+ CD25+ Treg cells and tumor-derived antigen-specific CD4+ Treg cells can be reversed by TLR8 signaling pathway in DCs independent mechanism, but requires the activation of TLR8-MyD88-IRAK4 signaling pathway." (PMID 30619286, 2018). "Tumor-secreted miRNAs (miR-21 and miR-29a) can function as ligands, binding to the receptors of the Toll-like receptor (TLR) family, namely, murine TLR7 and human TLR8." (PMID 28523250, 2017). "The small ligands IMMS activate both TLR7 and TLR8 similarly to the natural pathogens to yield a cascade of biochemical events that initially stimulate several type of cells, such as monocytes and NK/NKT, T, B, mast and tumor cells." (PMID 28582454, 2017). "Tumor-secreted miR-21 and miR-29a trigger a TLR-mediated prometastatic inflammatory response by binding as ligands to receptors of TLR family, namely murine TLR7 and human TLR8, in immune cells." (PMID 28231804, 2017). "Although the mechanisms responsible for the regulatory activity of tumor-infiltrating Vδ1 cells was not investigated in that paper, it seems to involve TLR8 signaling pathway, as suppression was reversed by TLR8 ligands." (PMID 25505472, 2014). "TLR1 and TLR8 are preferentially expressed on tumor cells, and a high expression of TLR1 and TLR8 (mRNA and protein) was observed in cancer tissues, showing for the first time that TLR1 and TLR8 in humans may be related to CRC." (PMID 25547486, 2014).
tumor (continued). "The discrepancy between the expression levels of TLR4 and TLR8 and the data obtained from in silico analysis could be due to the different origins, since the gene expression was evaluated in PBMC while bioinformatic dataset was obtained from tumor tissues." (PMID 40025339, 2025). "In terms of TLR ligand-targeted modulation of NK cells, TLR8 agonists (e.g., R848) and TLR9 agonists can respectively regulate immunomodulatory and cytotoxic NK cells, increase the expression of activation receptors such as NKG2D and NKp44, and synergistically enhance anti-tumor activity." (PMID 41488647, 2025). "Additionally, we did not see an increase in tumor-infiltrating DCs by scRNAseq, however, we were able to identify a distinct DC activation following TLR8 agonism and anti-PD-1 blockade." (PMID 39697344, 2024). "Thus, TLR8 agonists (loaded or not to nanoparticles or other carriers) can be considered a novel strategy able to promote anti-tumor immunity." (PMID 36672572, 2022). "Activation of TLR8 in cancer cells is found to prevent the induction of senescence in responder T cells and DCs, stimulate glucose uptake and glycolysis in CD4+ T cells, and induce apoptosis of MDSCs to enhance the anti-tumor effects of adaptive immune response." (PMID 35413927, 2022). "Tumor-secreted exosomal miR-21 and miR-29a can bind to murine TLR7 (Toll-like receptor 7) and human TLR8 (Toll-like receptor 8) in immune cells, inducing a TLR -mediated inflammatory response that may eventually provide suitable conditions for tumor metastasis." (PMID 34595207, 2021). "In addition to DNA and protein content, it is possible that chemotherapy may also trigger the release of RNA from dying tumor cells, which can in turn serve as a ligand for TLR7 or TLR8." (PMID 31619293, 2019). "Furthermore, human Toll-like receptor 8 (TLR8) signaling can directly target multiple types of tumors and prevent tumor-induced cell senescence through modulation of levels of endogenous secondary messenger cAMP in tumor cells." (PMID 31181772, 2019). "Another agonist of TLR7 and TLR8, namely R848 or resiquimod, loaded into β-cyclodextrin nanoparticles induced a functional re-orientation of the TME, in which the M2-like TAMs shifted toward a M1-like TAM phenotype, reducing tumor growth in multiple murine tumor models." (PMID 30349530, 2018). "Furthermore, tumor‐released miRNA binds murine TLR7 and human TLR8 in immune cells, leading to TLR‐induced prometastatic inflammatory response that may ultimately lead to tumor metastasis." (PMID 28665028, 2017). "Moreover, tumor-secreted miR-21 can function via binding as ligands to murine TLR7 and human TLR8 in immune cells, thereby triggering a TLR-mediated prometastatic inflammatory response that ultimately may lead to tumor growth and metastasis." (PMID 26116372, 2015). "Notably, CD4+regulatory T (Treg) cells can suppress the body's immune responses, while TLR8 can activate the TLR8-MyD88-IRAK4 signaling pathway through recognition of ligands to inhibit the immunosuppressive function of Treg cells, thereby enhancing the body's anti-tumour immunity." (PMID 38104080, 2023). "However, in vivo and in vitro experiments have shown that activation of toll-like receptor 8 (TLR8) signaling can block this mechanism to suppress T lymphocyte senescence and enhance antitumor immunity in the microenvironment, providing a new strategy for tumor immunotherapy." (PMID 36291773, 2022). "Consistent with their roles in immune surveillance, TLR4 and TLR8 are expressed in non-malignant and malignant cells, especially in tissues exposed to the external environmental, such as lung and the gastrointestinal tract, where may influence the tumor cell survival and the resistance to apoptosis." (PMID 40025339, 2025). "Surprisingly, the responses were not correlated with an increase in viral signaling proteins (RIG-I, TLR7, and TLR8), viral entry proteins (ICAM-1 and DAF), or PD-L1, nor was an inflamed tumor microenvironment found." (PMID 37569757, 2023).